HNF4A (hepatocyte nuclear factor 4 alpha)
Diseases named in the same sentence as HNF4A in open-access papers (continued):
Sharing a sentence is not in itself a finding about the gene and the disease.
diabetes (continued). "When overlaying this network with canonical pathways in NASH, HNF4A and HNF1A are connected to hepatic cholestasis, diabetes and FXR/RXR activation." (PMID 29216278, 2017). "We then consider the three common subtypes of sulfonylurea‐treated monogenic diabetes, HNF1A and HNF4A MODY and KCNJ11/ABCC8 permanent neonatal diabetes." (PMID 28556992, 2017). "The fact that different SNPs in the HNF4A region are associated with diabetes in different populations suggests that none of these alleles themselves are causative functional variants but that they may be in linkage disequilibrium with a nearby functioning allele." (PMID 25671620, 2015). "HNF4A, together with the related locus, HNF1A and also GCK also account for up to 80% of rare monogenic forms of diabetes." (PMID 24744783, 2014). "There is a significant clinical overlap between patients with hepatocyte nuclear factor (HNF)-1A and HNF4A maturity-onset diabetes of the young (MODY), two forms of monogenic diabetes." (PMID 23803251, 2013). "The strategy called genome-wide linkage study with subsequent positional cloning which led to the identification of the HNF4A and HNF1A genes, which were found to be responsible for 2 forms of monogenic diabetes, initially called MODY1 and MODY3, respectively." (PMID 22996131, 2012). "Mutations may arise de novo, and parents of HNF4A-mutation children might not have diabetes." (PMID 23032149, 2012). "Furthermore the study aimed at determining whether mutations in KCNJ11, ABCC8, HNF1A, HNF4A or INS are common in AAB negative diabetes." (PMID 20863361, 2010). "HNF4α plays a critical role in regulating metabolic processes, inflammation, and disease progression, especially in cancers like HCC and PDAC, as well as metabolic disorders such as MASLD, MASH, and diabetes." (PMID 40926269, 2025). "This enrichment was lower than observed in T2D cases and independent of parental diabetes history and after removing variants in HNF1A, HNF4A or HNF1B genes from the PGS (0.4 s.d." (PMID 40925988, 2025). "Overall, our work provides a valuable resource of HNF4A and HNF1A targets in human pancreatic and hepatic cells, with a focus on the beta cells which lie at the heart of diabetes pathophysiology, revealing potential therapeutic targets and pathways to guide future strategies for treating diabetes." (PMID 38909044, 2024). "In a prospective study on HNF1A-diabetes (n = 27) and HNF4A-diabetes (n = 7) not on SU at diagnosis, 25 of the 31 patients on insulin discontinued insulin but only 12 (48%) achieved an HbA1c of 7.5%23." (PMID 39025920, 2024). "HNF4α plays a key role in lipid and glucose metabolism and intersects with not just diabetes and circadian rhythms but also with liver cancer, although much remains to be elucidated about those interactions." (PMID 37600688, 2023). "A clinical prediction model (MODY probability calculator) has been developed previously, using 594 Europeans with HNF1A, HNF4A or GCK monogenic diabetes and 597 with types 1 and type 2 diabetes, and can be used to derive the pre-test probability of monogenic diabetes." (PMID 37033247, 2023). "In a USA study, monogenic diabetes genetic screening approach was modeled as being cost-effective at 6% yield and cost-saving at 30% yield for GCK, HNF1A, HNF4A, with an estimated combined prevalence of 2%, implicating the most clinically actionable changes to therapy." (PMID 37794142, 2023). "For example, neonatal onset (directed neonatal diabetes gene panel testing); retrospective mild fasting hyperglycaemia (characteristic of GCK); high HDL (HNF1A); neonatal macrosomia (HNF4A) and syndromic features present in patients with either HNF1B or mitochondrial forms (MIDD)." (PMID 37033247, 2023).
diabetes (continued). "In contrast to the age-related phenotype of HNF1A/HNF4A-MODY, GCK-MODY causes life-long stable mild fasting hyperglycemia from birth with a modest increase with age rather than true progressive diabetes as seen in HNF1A/HNF4A-MODY." (PMID 36257325, 2022). "Outside of our clinically referred to cohort, we found that most individuals with HNF1A- and HNF4A-MODY did not develop diabetes even by 50 years of age (∼50% and ∼80% in Geisinger and UK Biobank, respectively)." (PMID 36257325, 2022). "Notably, TFs linked to mature-onset diabetes of the young [MODY, HNF4A (MODY1), PDX1 (MODY4), and KLF11 (MODY7)] gain a significant number of target genes after 2 decades, which could explain how mutations in these genes can affect beta cell structure function to cause diabetes later in life." (PMID 36197983, 2022). "In mouse, it has been shown that full inactivation Hnf4a is embryonically lethal, while heterozygote knockout mice are normoglycemic and do not present diabetes features." (PMID 34295307, 2021). "The HNF family of TFs is implicated in mature onset diabetes of the young (MODY), and mutations in the HNF4α, HNF1α, and HNF1β genes cause MODY, a form of non-insulin-dependent diabetes mellitus." (PMID 34771521, 2021). "In addition, genes in the mature onset diabetes in young people (hsa04950) pathway (such as HES1, GCK, FOXA3, MAFA, HNF4A, HHEX, and PDX1) were increased in stages II to IV; these genes are related to insulin secretion and the maturation of pancreatic β-cells." (PMID 33897780, 2021). "This study, however, did not compare HNF1A diabetes with HNF4A, which bears many clinical similarities between each other." (PMID 32528556, 2020). "The finding of 8% of ABCC8 mutations in 85 individuals with sulfonylurea-sensitive diabetes, negative for HNF1A and HNF4A mutation, and without neonatal onset illustrate this principle." (PMID 32528556, 2020). "A final limitation is that we have investigated the prevalence of HNF1A-MODY only, as the most common form of monogenic diabetes, so the prevalence of other MODY subtypes, such as GCK-, HNF4A- or HNF1B-MODY in Croatia remains unknown." (PMID 29666556, 2018). "The optimum treatment for HNF1A/HNF4A maturity‐onset diabetes of the young and ATP‐sensitive potassium (KATP) channel neonatal diabetes, outside pregnancy, is sulfonylureas, but there is little evidence regarding the most appropriate treatment during pregnancy." (PMID 28556992, 2017). "In addition, studies on MODY in pregnant women with diabetes were largely limited to the screening of GCK, HNF1A and HNF4A genes." (PMID 28095440, 2017). "Similarly, we observed enrichment of genes associated with the molecular genetics of type 2 diabetes (T2D) and Maturity Onset Diabetes of the Young (MODY; e.g. Hnf1a, Hnf4a, Slc2a2, Gck) in βTC6." (PMID 28931935, 2017). "Moreover, this study is the first to describe the influence of diabetes on the expression of hepatic markers (ALB, AFP), HNF-4α and miR-122 in NOD fetus liver." (PMID 28319104, 2017). "HNF4α expression is markedly reduced in diabetes, obesity, non-alcoholic fatty liver disease (NAFLD) and high fat diet (HFD) feeding, likely resulting from increased free fatty acids (FFA), cholesterol and miR-34a expression." (PMID 27075303, 2016). "Four of the patients with no molecular diagnosis were only tested for the mitochondrial mutation, as their phenotype was not thought to be compatible with HNF1A or HNF4A diabetes." (PMID 27330718, 2016). "Given the fact that lean males exhibited a lower transporter expression compared to lean females, we assume that obesity or diabetes induced further reduction in Hnf4α was not sufficient to decrease transporter expression even more." (PMID 25710042, 2015).
diabetes (continued). "Most importantly, introducing the fat-1 gene into the diabetes context resulted in abrogating CRC development and cell proliferation, while suppressing the expression of HNF-4α, β-catenin and β-catenin/Tcf-responsive genes, and promoting epithelial differentiation." (PMID 25375205, 2014). "However, given a lack of GAD65/IA2 antibodies and a maternal family history of diabetes for three generations, she was referred for HNF1A and HNF4A genetic testing." (PMID 25015100, 2014). "Indeed, MEDICA analogs combine the two features of counteracting diabetes in animal models (e.g., Zucker, cp/cp, db/db, ob/ob), while mimicking (n-3) PUFA in suppressing HNF-4α transcriptional activity, and in activating AMPK." (PMID 25375205, 2014). "Consideration of genetic testing for HNF4A should therefore be considered in patients with clinical features suggestive of HNF1A monogenic diabetes but negative genotyping and those with a positive family history of macrosomia or neonatal hypoglycaemia." (PMID 23766565, 2013). "The merging of the three significantly effected networks generated a complex network with regulatory hubs formed by inflammation related genes (e.g. TNF-α, NF-κB), kinases (e.g. AKT, PI-3 kinase), and transcriptional regulators (HNF4A, EGR1, Jnk) as well as diabetes related genes (Insulin, Ins1)." (PMID 22606220, 2012). "The insulin signaling pathway in diabetes mellitus type 2 is regulated by a number of transcription factors, notably HNFs, especially MODY1 (HNF4α), which regulates a large fraction of the hepatic and pancreatic transcriptomes by binding directly to approximately half of the transcribed genes." (PMID 21731631, 2011). ",4HNF1A/HNF4A-MODY (HNF1A-MODY, MIM: 600495; HNF4A-MODY, MIM: 125850) are better treated with oral sulphonylureas whereas GCK-MODY (MIM: 125851) does not need treatment and is not at high risk of diabetes-related complications." (PMID 36257325, 2022). "Our data suggest that intensive close monitoring of the onset of diabetes may not be necessary for people with incidentally identified pathogenic variants in HNF1A and HNF4A due to a substantially lower risk of diabetes." (PMID 36257325, 2022). "The age at diagnosis of diabetes was higher in HNF4α- and HNF1β-MODY probands than in the other MODY types, including MODY X. MODY X probands exhibited higher fasting glucose levels and glucose levels at 60 min during an OGTT compared with those of GCK-, HNF1α-, and HNF4α-MODY probands." (PMID 34746319, 2021). "The lack of optimal glycaemic control in our study may have resulted from clinical inertia or limited experience among local clinicians in managing HNF1A/HNF4A-MODY and previous advice advocating a trial of sulfonylureas even in those with longstanding diabetes." (PMID 30229274, 2018). "Our study suggests that, in individuals with HNF1A/HNF4A-MODY with a longer duration of diabetes (>11 years) at time of genetic test, rather than ceasing current treatment, a sulfonylurea should be added to existing therapy, particularly in those who are overweight or obese and have a high HbA1c." (PMID 30229274, 2018). "Incorporating the fat-1 transgene in the diabetes context, or oral MEDICA treatment, resulted in ameliorating the diabetic phenotype and in abrogating CRC, with decrease in ACF load, cell proliferation and the expression of HNF-4α, β-catenin, and β-catenin-responsive genes." (PMID 25375205, 2014). "Carcinogen-induced CRC is shown here to be promoted by the diabetes context, in terms of increased aberrant crypt foci (ACF) load, cell proliferation and epithelial dedifferentiation, being accompanied by increase in the expression of HNF4α, β-catenin, and β-catenin-responsive genes." (PMID 25375205, 2014). "Hence, the absence of a history of diabetes in the parents should not preclude sequencing of the HNF4A gene." (PMID 23032149, 2012).
diabetes (continued). "Indeed, mutations in the human HNF4α are associated with maturity onset diabetes of the young (MODY) and late onset type II diabetes; yet, how these HNF4α lesions lead to diabetes has not been established." (PMID 19668342, 2009). "In conclusion, the present study allowed identifying a novel positive regulatory link between HNF4α (MODY1) and GIP incretin in the intestine and paves the way for further studies as to whether this molecular relationship may be therapeutically exploited in metabolism disorders including diabetes." (PMID 30862908, 2019). "However, only 58% of individuals with HNF1A/HNF4A-MODY were on diet or sulfonylurea alone at 2 years and, overall, just 36% of individuals with HNF1A/HNF4A-MODY who changed treatment achieved the good glycaemic control (≤58 mmol/mol [≤7.5%]) needed to avoid diabetes complications." (PMID 30229274, 2018). "HNF4A-MODY subjects have similar progressive diabetic phenotype to HNF1A-MODY subjects, except that HNF4A mutations are associated with macrosomia, transient and persistent neonatal hypoglycaemia, later age of diabetes onset and the absence of low renal threshold." (PMID 23803251, 2013). "Of the adult diabetes patients with no molecular diagnosis, seven had complete testing of HNF1A and HNF4A including multiplex ligation‐dependent probe amplification (MLPA) for deletions and duplications." (PMID 27330718, 2016). "A common pattern emerged whereby patients that do not remit diabetes (T2D-NoR) displayed signifciantly higher expression levels for FGF21, HNF4α, CYP7A1, β-Klotho, GS, and FGFR4, compared to the No-T2D and T2D-R groups." (PMID 25664662, 2015). "Due to the family history of diabetes (mother and grandmother on treatment with oral hypoglycemic drugs), genetic tests for the most common forms of MODY were performed (GCK-, HNF1A-, and HNF4A- MODY) and found negative." (PMID 36294752, 2022). "Fetal growth on ultrasonography may provide a surrogate of fetal inheritance in HNF4A MODY and KATP neonatal diabetes in the absence of a confirmatory antenatal genetic test, and may be useful in guiding the most appropriate management." (PMID 28556992, 2017). "Moreover, hepatic expression levels of FGF21, CYP7A1, HNF4α, β-Klotho, FGFR4, and GS were higher in T2D patients that do not remit diabetes after RYGB surgery." (PMID 25664662, 2015). "HNF1A/HNF4A-MODY diabetes should be considered in a young, pregestational, obese woman with symptomatic or asymptomatic hyperglycemia without ketoacidosis and a positive family history of diabetes or a history of gestational diabetes as a potential indicator of autosomal dominant inheritance." (PMID 39902162, 2024). "However, because of the lack of standard antibody testing in those with diabetes, a proportion of individuals with MODY subtypes (such as HNF1A/HNF4A-MODY) may be misdiagnosed as having type 1 diabetes." (PMID 37897565, 2023).
MODY (161 papers, 2008 to 2026). "A mutation in the HNF4α gene is the major monogenic cause of maturity-onset diabetes of the young type 1 (MODY1)." (PMID 40940746, 2025). "HNF4A is a critical transcriptional regulator involved in glucose metabolism and pancreatic β-cell function, and mutations in HNF4A are closely linked to maturity-onset diabetes of the young type 1 (MODY1)." (PMID 40995593, 2025). "Functionally defective mutation of HNF4α causes the maturity-onset diabetes of the young (MODY), which is characterized by pancreatic β-cell dysfunction and impaired insulin secretion." (PMID 40940746, 2025). "Variants in the HNF1A and HNF4A genes are associated with maturity-onset diabetes of the young (MODY)." (PMID 38855865, 2024). "Heterozygous pathogenic variants in HNF4A gene cause maturity-onset diabetes of the young type 1 (MODY1)." (PMID 37711893, 2023). "Mutation or dysregulation of the Hnf4a gene is associated with human diseases such as maturity-onset diabetes of the young (MODY) and HCC19,20." (PMID 34732735, 2021). "More than 2 decades ago, mutations in the HNF4A gene were identified as the first monogenic cause of maturity-onset diabetes of the young type 1 (MODY1), usually diagnosed before the age of 25 years in patients with negative islet cell autoantibodies." (PMID 31875549, 2019). "On the other hand, germline HNF4A mutations are linked to maturity-onset diabetes of the young (MODY)-1, which is an atypical form of type 2 diabetes (T2D)." (PMID 29899848, 2018). "In line with HNF4α’s important metabolic regulatory roles, loss-of-function mutations in the human HNF4A gene have been linked to maturity onset diabetes of the young (MODY) and to type 2 diabetes." (PMID 27618178, 2016). "HNF4A mutations cause hyperinsulinaemic hypoglycaemia and maturity-onset diabetes of the young (MODY)." (PMID 24299156, 2014). "Mammalian HNF4α proteins function in many processes including lipid and glucose metabolism, and HNF4α mutations in humans are associated with maturity onset diabetes of the young type 1." (PMID 23935515, 2013). "Dysfunction of hepatocyte nuclear factor 4α (HNF4α) has been linked to maturity onset diabetes of the young (MODY1), diabetes type II and possibly to renal cell carcinoma (RCC)." (PMID 22140441, 2011). "Mutations in the HNF4A gene are linked to diabetes type II and maturity onset diabetes of the young type 1 (MODY1)." (PMID 22140441, 2011). "Mutations in the HNF4α gene are associated with maturity onset diabetes of the young type 1 (MODY1)." (PMID 20003313, 2009). "HNF4α mutations have been shown to play role in an autosomal dominant manner in families with an atypical form of T2D known as maturity onset diabetes of the young (MODY1)." (PMID 20003313, 2009). "Abnormalities in HNF4a are commonly associated with a high incidence of maturity-onset diabetes of the young (MODY), with MODY1 patients exhibiting defects in insulin secretion stimulated by glucose and arginine, indicating a progressive loss of pancreatic β-cell function." (PMID 40469443, 2025). "First of all, HNF4A gene mutations have been associated with maturity-onset diabetes of the young (MODY), a monogenic form of diabetes presenting early in life and characterized by deficient glucose-induced insulin secretion by dysfunctional pancreatic β-cells." (PMID 32998360, 2020). "The most common mutations associated with MODY involve glucokinase (Gck) (MODY 2), hepatic nuclear factor 1-alpha (Hnf1α) (MODY 3), and hepatic nuclear factor 4-alpha (Hnf4α) (MODY 1), which together account for approximately 94% of MODY cases." (PMID 40149950, 2025). "In India, targeted next-generation sequencing of 10 MODY genes in 56 patients identified potentially pathogenic variants in HNF4A, GCK, HNF1A, PDX1, HNF1B, NEUROD1, and PAX4 in 11 individuals, suggesting a more complex etiological spectrum in this population." (PMID 41153735, 2025).